ZNF569 (zinc finger protein 569)
Description:
May be involved in transcriptional regulation.
Synonyms: FLJ32053; ZAP1; Zfp74; ZNF
Tractability: PROTAC: ubiquitination databases record sites on it.
Gene: Protein-coding gene on chromosome 19 (37,410,878 to 37,469,282, reverse strand). Ensembl gene ENSG00000196437.
Subcellular location: Nucleus
Subcellular location (Human Protein Atlas): Golgi apparatus; Nucleoplasm; Vesicles
Pathways (Reactome):
Gene expression (Transcription): Generic Transcription Pathway
Gene Ontology:
Molecular function: protein binding; DNA-binding transcription factor activity, RNA polymerase II-specific; RNA polymerase II cis-regulatory region sequence-specific DNA binding; sequence-specific double-stranded DNA binding
Biological process: regulation of transcription by RNA polymerase II; regulation of DNA-templated transcription
Cellular component: nucleus
Genetic constraint (gnomAD): Loss-of-function variants: 38 observed, 57.6 expected, observed/expected ratio (o/e) 0.66, 90% interval 0.51 to 0.87. The upper end of that interval is the gene's LOEUF score, 0.87, which puts it in group 3 of 6, group 1 being the genes least tolerant of losing a copy. Missense variants: 666 observed, 851.96 expected, observed/expected ratio (o/e) 0.78, 90% interval 0.73 to 0.83. Synonymous variants: 241 observed, 275.56 expected, observed/expected ratio (o/e) 0.87, 90% interval 0.79 to 0.97.
Homologues: Orthologues: chimpanzee ZNF569 (100% identical), macaque ZNF569 (99% identical), rabbit ZNF569 (93% identical), pig ZNF569 (93% identical), guinea pig ZNF569 (91% identical), rat Zfp74 (85% identical), mouse Zfp74 (84% identical), zebrafish zgc:66472 (15% identical), Drosophila melanogaster mld (14% identical), zebrafish si:ch211-148l7.4 (11% identical). Paralogues in human: ZNF184 (49% identical), ZNF84 (49% identical), ZNF91 (49% identical), ZNF160 (48% identical), ZNF208 (47% identical), ZNF99 (45% identical), ZNF107 (45% identical), ZNF420 (44% identical), ZNF347 (44% identical), ZNF729 (43% identical), ZNF845 (41% identical), ZNF665 (41% identical), and 24 more.
Diseases named in the same sentence as ZNF569 in open-access papers:
ZNF569 is named in the same sentence as 6 diseases in open-access papers, as found by Europe PMC text mining. Sharing a sentence is not in itself a finding about the gene and the disease. The quoted sentences say what the papers report.
Barrett esophagus (2 papers, 2018 to 2020). Esophageal lesion lined with columnar metaplastic epithelium which is flat or villiform. "In the same vein, ZNF569 promoter hypermethylation has been associated with glandular lesions, like Barrett’s esophagus in comparison with the normal esophagus." (PMID 33292587, 2020). "TFPI2, TWIST1, ZNF345 and ZNF569 methylation have promise as diagnostic biomarkers for Barrett’s oesophagus when used in combination with a simple and cost effective non-endoscopic cell collection device." (PMID 29084829, 2018).
cancer (2 papers, 2018 to 2024). A tumor composed of atypical neoplastic, often pleomorphic cells that invade other tissues. "ZNF345 and ZNF569 are novel methylation markers that have not previously been reported to be hypermethylated in cancer." (PMID 29084829, 2018).
tumor (1 paper, 2021). "For example, ZNF545, ZNF569, ZNF383, and ZNF331 are reported to act as tumor suppressor genes, while ZNF147, ZNF217, ZNF278, GLI1, and Evi9 promote tumor progression." (PMID 33566221, 2021).
ZNF569 also shares sentences with these, for which no sentence is quoted: Zinc deficiency (7 papers); infection (6); cryptococcosis (4).